TCIRG1 (T cell immune regulator 1, ATPase H+ transporting V0 subunit a3)
Diseases named in the same sentence as TCIRG1 in open-access papers (continued):
Sharing a sentence is not in itself a finding about the gene and the disease.
hepatocellular carcinoma (9 papers, 2019 to 2025). A malignant tumor that arises from hepatocytes. "T cell immune regulator 1 (TCIRG1), also known as T cell immune response cDNA7 (TIRC7), has been implicated in promoting progression and metastasis in malignancies, encompassing prostate cancer, breast cancer, and hepatocellular carcinoma." (PMID 41180155, 2025). "The TCIRG1 was up-regulated in hepatocellular carcinoma and significantly associated with unfavorable prognosis of hepatocellular carcinoma patients." (PMID 33101364, 2020). "TCIRG1 is highly expressed in various malignancies, including prostate cancer, breast cancer, and hepatocellular carcinoma, and is involved in multiple pathways that promote tumor growth, invasion, and metastasis." (PMID 41180155, 2025). "TCIRG1, one of the V-ATPase subunits, is abnormally overexpressed in patients with recurrent hepatocellular carcinoma, and enhances the ability of metastasis by regulating the growth, death, and epithelial to mesenchymal transition of cancer cells." (PMID 35265613, 2022). "TCIRG1 is upregulated and critical in the invasion of melanoma cells, breast cancer cells, and hepatocellular carcinoma cells." (PMID 36230507, 2022). "PLXDC1 increases invasion in gastric cancer, and TCIRG1 is an osteoclast-specific vacuolar proton pump subunit that acts as a metastasis enhancer in hepatocellular carcinoma." (PMID 33420367, 2021). "TCIRG1, is recognized as T cell immune regulator 1, constitutes the V0a3 subunit of vacuolar ATPase (V-ATPase), which is involved in varieties of malignant tumors, such as melanoma, breast cancer, and hepatocellular carcinoma." (PMID 38238671, 2024). "Previous studies revealed that TCIRG1 was widely up-regulated in numerous tumors, such as hepatocellular carcinoma, esophageal adenocarcinoma and breast cancer, which might be associated with autophagic sequestration and degradation." (PMID 31681747, 2019). "According to hepatocellular carcinoma studies, however, TCIRG1 promotes the proliferation and epithelial-mesenchymal transition (EMT) of hepatocellular carcinoma cells and is a poor prognostic factor for patients with hepatocellular carcinoma." (PMID 36081667, 2022). "In addition, in hepatocellular carcinoma (HCC), TCIRG1 can act as a metastasis enhancer by regulating HCC cell growth, death and epithelial–mesenchymal transition (EMT), and may also be a therapeutic target for cancer and metastasis." (PMID 37649034, 2023).
periodontal disease (7 papers, 2013 to 2025). "TCIRG1 expression was found to induce the bone resorption activity of osteoclasts in periodontal disease." (PMID 36545026, 2022).
clear cell renal cell carcinoma (6 papers, 2021 to 2025). "And we analyzed a proteogenomic data of clear cell renal cell carcinoma in a Chinese population, it was also found that high TCIRG1 expression predicted poor OS in ccRCC patients." (PMID 37649034, 2023). "The validity that TCIRG1 can accelerate the development of renal clear cell carcinoma was also confirmed in this work by using certain testable experiments." (PMID 36230507, 2022). "The molecular mechanisms behind TCIRG1 and its possible role in the development of clear cell renal cell carcinoma are still poorly understood." (PMID 36230507, 2022). "Our research is the first to thoroughly examine TCIRG1’s function in clear cell renal cell carcinoma prognosis, immunity, and treatment." (PMID 36230507, 2022). "The aim of the present study was to determine whether and how the glycolysis-related biomarker TCIRG1 affects aerobic glycolysis, the tumor microenvironment (TME) and malignant progression of clear cell renal cell carcinoma (ccRCC)." (PMID 37649034, 2023).
breast carcinoma (5 papers, 2017 to 2025). "For comparison, other V-ATPase subunits, ATP6v1c2 or ATP6v0a3/TCIRG1, are only overexpressed or genomically amplified in 7% of breast cancers, respectively, and their overexpression or genomic amplification didn't significantly correspond with effects on patient survival." (PMID 28504970, 2017).
osteosclerosis (4 papers, 2022 to 2025). Abnormally high bone density. "“T-cell immune regulator 1” (Tcirg1) is a key genetic factor in infantile malignant osteosclerosis, with mutations identified in most affected patients." (PMID 40995561, 2025). "TCIRG1 was first identified in osteosclerosis, and study has shown that TCIRG1 mutation is a common cause of human autosomal recessive osteosclerosis." (PMID 37649034, 2023). "In previous reports, the deletion of TCIRG1 was shown to lead to an increase in bone density, which can lead to the development of osteosclerosis." (PMID 36230507, 2022). "T-cell immune regulator 1 (TCIRG1), also known as V-type proton atpase 116 kDa subunit a3 or T-cell immune response cDNA 7 protein (TIRC7), was first identified in osteosclerosis, and mutations in TCIRG1 are a common cause of human autosomal recessive osteosclerosis." (PMID 37649034, 2023). "He had unique metadiaphyseal splaying and osteosclerosis, vertebral end‐plate osteosclerosis, and cortical thinning of long bones but no mutation was detected of SLC29A3, TNFRSF11A, TCIRG1, LRRK1, or CSF1R associated with DSS." (PMID 35991533, 2022).
congenital neutropenia (3 papers, 2022 to 2025). "We previously identified a novel heterozygous missense mutation, R736S, in TCIRG1, as the cause of severe congenital neutropenia (SCN) in a large multigenerational family." (PMID 40964614, 2025). "The identification of TCIRG1 mutations as a genetic cause of congenital neutropenia has important clinical implications for diagnosis and patient management." (PMID 40964614, 2025). "While congenital neutropenia has various genetic causes, recent studies have linked TCIRG1 mutations to this condition." (PMID 40964614, 2025). "We previously identified heterozygous TCIRG1 mutations, including R736S, R736C, R736P, and E722D, in individuals with congenital neutropenia." (PMID 40964614, 2025). "By leveraging patient-derived iPSCs and genome editing, we have established a mechanistic link between TCIRG1 dysfunction and congenital neutropenia." (PMID 40964614, 2025).
glioblastoma multiforme (3 papers, 2021 to 2023). "Furthermore, a correlation of TCIRG1 expression and immune infiltration levels has been found in the most malignant brain glioma glioblastoma multiforme." (PMID 35327495, 2022). "In glioblastoma multiforme (GBM), TCIRG1 is considered as a prognostic biomarker and an indicator of immune infiltration." (PMID 37649034, 2023).
neutropenia (3 papers, 2022 to 2025). A decrease in the number of neutrophils found in the blood. "While neutropenia has diverse genetic and acquired causes, recent studies have implicated mutations in the TCIRG1 (T-cell immune regulator 1) gene in a subset of cases." (PMID 40964614, 2025). "This study provides new insights into the molecular basis of TCIRG1-associated neutropenia and highlights potential avenues for therapeutic intervention." (PMID 40964614, 2025). "As the unfolded protein response and apoptosis appear to play a central role in TCIRG1-associated neutropenia, experimental therapeutic approaches targeting these pathways should be explored." (PMID 40964614, 2025). "In this study, we utilized patient-derived induced pluripotent stem cells (iPSCs) to model TCIRG1-associated neutropenia and elucidate the mechanistic consequences of TCIRG1 mutations on myeloid differentiation." (PMID 40964614, 2025). "However, emerging evidence suggests that TCIRG1 mutations can also impair neutrophil development and survival, leading to congenital neutropenia." (PMID 40964614, 2025). "However, why specific heterozygous TCIRG1 mutations at R736 and E722 lead to neutropenia remains unknown." (PMID 40964614, 2025). "Our understanding of TCIRG1 and how it may cause neutropenia is incomplete." (PMID 40964614, 2025). "CLPB-related neutropenia also accounted for 10% of cases, followed by defects in the TCIRG1 (eight cases), CXCR4 (seven cases), and SRP72 genes (seven cases)." (PMID 41383606, 2025). "Despite its established role in bone homeostasis, the precise mechanism by which TCIRG1 dysfunction results in neutropenia remains unclear." (PMID 40964614, 2025). "One of the most intriguing aspects of TCIRG1-associated neutropenia is the apparent lack of defects in other tissues, despite the gene’s well-established role in osteoclast function and expression in other tissues." (PMID 40964614, 2025). "An alternative hypothesis is that the molecular mechanism of TCIRG1-associated neutropenia is not due to a simple loss-of-function, but rather a gain-of-function effect caused by the specific mutations at R736 and E722." (PMID 40964614, 2025).
renal carcinoma (3 papers, 2022 to 2025). A carcinoma arising from the epithelium of the renal parenchyma or the renal pelvis. "While TCIRG1 and Treg cell coexpression in renal carcinoma cells was confirmed, the precise mechanisms and pathways driving tumor growth, invasion, and metastasis remain insufficiently explored." (PMID 41180155, 2025). "In addition, we used the scRNA-seq dataset GSE139555 from renal cancer patients and found that TCIRG1 expression was higher in renal tumors tissues than in normal renal tissues, which is consistent with our results in TCGA-KIRC." (PMID 37649034, 2023). "Finally, the findings from our in vitro study showed that the knockdown of TCIRG1 significantly reduced the ability of renal cancer cells to migrate, which is consistent with the evidence from previous reports." (PMID 36230507, 2022).
rheumatoid arthritis (3 papers, 2018 to 2025). A chronic, systemic autoimmune disorder characterized by inflammation in the synovial membranes and articular surfaces. "We also found a heterozygous P/LP variant in TCIRG1 (c.1767-2A>G) in a 66-year-old man with chronic neutropenia and personal and family history (mother) of rheumatoid arthritis." (PMID 40309770, 2025).
Alzheimer disease (2 papers, 2022 to 2024). A progressive, neurodegenerative disease characterized by loss of function and death of nerve cells in several areas of the brain leading to loss of cognitive function such as memory and language. "Interestingly, TCIRG1 has a separate missense variant (TCIRG1 11:67,810,477:C > T) that was identified to segregate in 3 separate families with early onset Alzheimer’s disease (EOAD)." (PMID 35699875, 2022).
Hydrocephalus (2 papers, 2020 to 2023). Hydrocephalus is an active distension of the ventricular system of the brain resulting from inadequate passage of CSF from its point of production within the cerebral ventricles to its point of absorption into the systemic circulation. "The typical clinical neurological presentation of TCIRG1-related ARO patients was also hydrocephalus, myotonia, neuropsychic and psychomotor retardation, compromised vision, and heavy nasal breathing." (PMID 37168803, 2023).
ovarian carcinoma (2 papers, 2021 to 2022). A malignant neoplasm originating from the surface ovarian epithelium. "Taken together, these results demonstrated that TCIRG1 knockdown could decrease the proliferation ability of ovarian cancer cells in vitro." (PMID 36081667, 2022). "TCIRG1 was selected as high priority markers for next study because it showed the higher coefficient in genetic models, and there are currently few studies in ovarian cancer." (PMID 36081667, 2022).
periodontitis (2 papers, 2013 to 2022). An acute or chronic inflammatory process that affects the tissues that surround and support the teeth. "Five genes (i.e., FMNL1, MANSC1, PLAUR, RNASE6, and TCIRG1) were identified as crosstalk biomarkers linking PD and periodontitis." (PMID 36545026, 2022). "The main findings of the current study identified five hub crosstalk genes (i.e., FMNL1, MANSC1, PLAUR, RNASE6, and TCIRG1) to be the linking mechanisms between periodontitis and PD." (PMID 36545026, 2022). "In periodontitis, MANSC1 was negatively correlated and the other four hub crosstalk genes (FMNL1, PLAUR, RNASE6, and TCIRG1) were positively correlated with five hub IRRGs, namely, AQP9, C5AR1, CD14, CSF3R, and PLAUR." (PMID 36545026, 2022).
eczema (1 paper, 2021). "Specifically, this was the case for a TCIRG1 variant in a patient with pancytopenia, an IL36RN variant in a patient with refractory eczema, and in a UNC13D variant in a patient with hemophagocytic lymphiohistiocytosis." (PMID 34992599, 2021).
glioma (1 paper, 2022). A benign or malignant brain and spinal cord tumor that arises from glial cells (astrocytes, oligodendrocytes, ependymal cells). "The protein encoded by TCIRG1 is a subunit of H+-ATPase, and a prognostic marker and immune infiltration marker in patients with glioma." (PMID 36081667, 2022).
lymph node metastasis (1 paper, 2023). "In addition, we also investigated the relationship between TCIRG1 expression and the clinicopathological characteristics in KIRC patients, and found that the expression level of TCIRG1 was higher in KIRC patients with poorer tumor differentiation, lymph node metastasis, and high clinical stage." (PMID 37649034, 2023).
osteomalacia (1 paper, 2016). Disorder caused by an interruption of the mineralization of organic bone matrix leading to bone softening, bone pain, and weakness. "Thus, in contrast to patients carrying TCIRG1 mutation, patients carrying CLCN7 mutation do not seem to suffer from osteomalacia." (PMID 26346547, 2016).
pulmonary arterial hypertension (1 paper, 2021). Pulmonary arterial hypertension (PAH) is a group of diseases characterized by mean pulmonary artery pressure >20 mmHg and elevated pulmonary arterial resistance leading to right heart failure. "According to another study, ATP6i (TCIRG1) mutations lead to pulmonary arterial hypertension." (PMID 34266467, 2021). "In our study, 3 children who died of pulmonary haemorrhage all had TCIRG1 mutations, but pulmonary haemorrhage and pulmonary arterial hypertension may also be related to the aggravation of pulmonary symptoms caused by high-dose chemotherapy and massive fluid infusion." (PMID 34266467, 2021).
rickets (1 paper, 2015). Bone softening and weakening usually caused by deficiency or impaired metabolism of vitamin D. Deficiency of calcium, magnesium, or phosphorus may also cause rickets. "Radiograph and micro-CT analysis demonstrated that that the Tcirg1 KO mice were strikingly similar to the Snx10 KD mice by radiograph and micro-CT, with lack of cortical bone, metaphyseal cupping and fraying, and non-mineralized condyles and articulations, all characteristic of rickets." (PMID 25811986, 2015).
schizophrenia (1 paper, 2019). A major psychotic disorder characterized by abnormalities in the perception or expression of reality. "Moreover, four DMRs were located at genes (VPS52, TCIRG1, and TRIM39) that were found to be differentially methylated in the largest schizophrenia (SCZ) whole-blood epigenome-wide association study (EWAS) to date." (PMID 31639064, 2019).
Thrombocytopenia (1 paper, 2025). A reduction in the number of circulating thrombocytes. "However, a related study revealed a statistically significant correlation between TCIRG1 mutation and thrombocytopenia, suggesting that this gene mutation was more aggressive." (PMID 41204604, 2025).
cancer (12 papers, 2014 to 2025). A tumor composed of atypical neoplastic, often pleomorphic cells that invade other tissues. "Knowing that immunocheckpoint inhibitors (ICIs) are a significant new group of tumor immunotherapy drugs, we used the TISIDB database to analyze the correlation between the expression level of TCIRG1 and ICIs in different human cancer types." (PMID 37649034, 2023). "The pan-cancer examination of TCIRG1 expression revealed that the expression of TCIRG1 was higher in some cancer tissues than in healthy tissues, including BLCA, CHOL, GBM, HNSC, KIRC, and LGG." (PMID 36230507, 2022). "In earlier research, TCIRG1 was found to be dysregulated in several cancers and to accelerate the growth of various malignancies." (PMID 36230507, 2022). "TCIRG1 has been reported to be overexpressed in several cancers and plays an important role in T cell activation." (PMID 35327495, 2022). "We then confirmed the computationally predicted differential binding of the top CL1-specific TF, RARα, at chr11:68,043,640–68,043,657 (GRCh38/hg38) in the promoter of TCIRG1, a gene that has a function in bone remodeling and cancer metastasis." (PMID 36266270, 2022). "In this study, we first conducted a pan-cancer investigation and found that TCIRG1 was expressed significantly in several cancer types, and the results of GEO and UALCAN consistently showed that TCIRG1 expression was noticeably increased in KIRC samples." (PMID 36230507, 2022). "We also analyzed the relationship between TCIRG1 and somatic mutations, TMB, DNA methylation, cancer stemness, and immune infiltration." (PMID 36230507, 2022). "Apart from BIRC5, GMIP, IFI16, and TCIRG1, other genes didn’t show significant differences in individual cancer stages." (PMID 35237298, 2021). "We initially assessed TCIRG1 mRNA expression in 28 human cancer and normal tissues using a combination of data from the TCGA and GTEX datasets to investigate the potential involvement of TCIRG1 in carcinogenesis and progression." (PMID 36230507, 2022). "However, the mechanism by which TCIRG1 promotes cancer cell migration and invasion has not been fully elucidated, and in a previous report, isoforms of the V-ATPase subunit have been shown to play a key role in cancer cell invasion." (PMID 36230507, 2022).